MTOR (mechanistic target of rapamycin kinase)
Diseases named in the same sentence as MTOR in open-access papers (continued):
Sharing a sentence is not in itself a finding about the gene and the disease.
chordoma (continued). "Both brachyury and mTOR are known to upregulate HIF-1α, suggesting a possible connection between dysregulated hypoxia signaling, physaliferous morphology, and establishment of a ferroptosis-susceptible state in chordoma." (PMID 36387127, 2022). "Although the precise composition of physaliferous vacuoles remains unclear, chordoma and ccRCC share additional similarities, including resistance to chemotherapy and modest mutational burdens enriched in chromatin modifier and PI3K/mTOR pathway alterations." (PMID 36387127, 2022). "Moreover, PI3K and mTOR are regulated by receptor tyrosine kinases (RTKs), of which several appear to be activated in most chordoma tumors." (PMID 36387127, 2022). "Finally, the MTOR inhibitor MLN0128 (sapanisertib) decreased activity of the PI3K-AKT-MTOR pathway in vivo in a clival chordoma PDX model." (PMID 32737414, 2020). "The authors suggested that a majority of chordomas may respond to mTOR inhibitors or mTOR inhibitors in combination with other drugs." (PMID 32737414, 2020). "Given our observations that U-CH2 is inhibited by AZD2014, a highly specific inhibitor of mTOR which inhibits both mTORC1 and mTORC2 activity, we hypothesize that mTORC2 has a critical role in promoting chordoma proliferation or survival." (PMID 32737414, 2020). "Monotherapy of TKIs is recommended as the first-line management, and combination therapy (two TKIs or TKI plus mTOR inhibitor) may be the choice for drug-resistant chordoma." (PMID 30775316, 2019). "In addition, IM plus sirolimus was used in 10 patients with IM-refractory chordoma and activated mTOR." (PMID 30775316, 2019). "Combined therapy (two TKIs or TKI plus mTOR inhibitor) may be the choice for drug-resistant chordoma." (PMID 30775316, 2019). "The mTOR protein is located in the cytoplasm of chordoma cell." (PMID 25793716, 2015). "However, the mTOR pathway was partially activated in endophytic chordoma than the exophytic chordoma, but the TGF-β1 was down regulated in endophytic chordoma." (PMID 25793716, 2015). "The role of TGF-β1 in PI3K/Akt/mTOR pathways in chordoma needs further studied." (PMID 25793716, 2015). "The mTOR signaling channel has been regarded as an important channel for intracellular signal transduction that affects cell growth, tumor formation and cell invasion, including chordoma." (PMID 25793716, 2015). "In conclusion, the consistent activation of AKT, the recurrent activation of upstream EGFR and of downstream effectors like p70S6K and mTOR, together with frequent loss of TSC1 and PTEN gene loci, all indicate that the PI3K/AKT pathway is an important mediator of transformation in chordoma." (PMID 22613809, 2011). "Nevertheless, the involvement of the AKT/mTOR pathway in chordoma is clear." (PMID 22613809, 2011). "The evidence of AKT activation in a small subgroup of patients has, moreover, led to test the adjunctive administration of the mammalian target of rapamycin (mTOR) inhibitor sirolimus to patients with secondary IM resistant chordomas demonstrating a re-establishment of tumour response." (PMID 20109225, 2010). "On the basis of p-mTOR and or p-p70S6K expression there is evidence indicating that 65% of the chordomas studied may be responsive to mTOR inhibitors, rapamycin or its analogues, and that patients may benefit from combined therapy including drugs that inhibit AKT." (PMID 19401700, 2009). "We consider that the 9 (20%) chordomas that do not express mTOR (total and phosphorylated) protein as assessed by IHC (five of these nine revealed only one mTOR allele (two cases with both alleles, two cases no data)) are unlikely to respond to mTOR inhibitors." (PMID 19401700, 2009). "Phosphorylated p70S6 kinase and p-mechanistic target of rapamycin (p-mTOR) have been found in 84.6% and 76.9% cases of BNCTs, respectively, paralleling the upregulation of the m-TOR pathway in chordomas." (PMID 39001221, 2024).
chordoma (continued). "Chordomas commonly activate pathways such as EGFR, PDGFβ, IGFR1, IGF1, mTOR, MET, and PI3K and involve chromatin remodeling genes such as ARID1A, PBRM1, and SETD2." (PMID 39193055, 2024). "Treating these chordoma cells with palbociclib (CDK4/6 inhibitor), rapamycin (mTOR inhibitor) or the pan-PI3K inhibitor buparlisib significantly reduced cell viability." (PMID 37046638, 2023). "To further investigate this issue, we analysed the activation state of the mTOR pathway in both the primary tumour and CH3 chordoma cell line." (PMID 36983607, 2023). "We investigated the effectivity of the pan-PI3K inhibitor buparlisib and mTOR inhibitor rapamycin as single agents, as well as in combination with the CDK4/6 inhibitor palbociclib, in chordoma cell lines." (PMID 37046638, 2023). "Among them, copy number loss at the PTEN gene locus on chromosome 10q23.3 is the most common genomic alteration in chordomas, affecting PI3K/AKT/mTOR signaling." (PMID 37046638, 2023). "The primary targets involved in chordoma are receptor tyrosine kinases (RTKs) and their downstream signaling, including the PI3K/AKT/mTOR." (PMID 37111759, 2023). "Chordoma tumors are known to overexpress multiple kinases (included PDGFR-α, PDGFR-β, c-Kit, c-Met, pAKT, mTOR, HER2, VEGFR, and EGFR) which are involved in a multitude of cellular functions relevant to cancer pathogenesis." (PMID 36505864, 2022). "report that the expression of PTEN is higher in adjacent normal tissues than that in sacral chordomas, and PTEN-negative expression and mTOR-positive expression are related to the invasion of tumor." (PMID 36520826, 2022). "At present, the research on the molecular mechanism of chordoma mainly includes receptor tyrosine kinase and its downstream signaling pathways, Src/Stat3 signaling pathway and PI3K/AKT/mTOR pathway." (PMID 34888345, 2021). "Out of these compounds, the mTOR inhibitor AZD2014, was the most potent against chordoma cell lines (IC50 0.35 μM U-CH1 and 0.61 μM U-CH2)." (PMID 32737414, 2020). "Analysis of 50 chordomas showed that a high percentage of tumors were positive for p-AKT, piTSC2, p-mTOR, total mTOR, p-P70S6K, p-RPS6, p-4EBPI and eIF-4E45." (PMID 32737414, 2020). "The down-regulation of miR-155 reduces the malignancy of chordoma cells, and enhances sensitivity to anti-cancer drugs by increasing the expression of PTEN and activating PI3K-Akt-mammalian target of rapamycin (mTOR) signaling." (PMID 32595638, 2020). "Inhibitors of the mTOR pathway (sirolimus) and inhibitors of EGFR (cetuximab/gefitinib) have also been used in cases of resistant chordomas or metastatic chordoma of the sacrum." (PMID 26391590, 2015). "Chordomas were positive for p-AKT (92%), p-TSC2 (96%), p-mTOR (27%), total mTOR (75%), p-p70S6K (62%), p-RPS6 (22%), p-4E-BP1 (96%) and eIF-4E (98%)." (PMID 19401700, 2009). "Overall, data indicate that the primary chordoma tumour and, to a lesser extent, its derived CH3 cells, exhibit mTOR hyperactivation that may be targeted by a specific pharmacological treatment." (PMID 36983607, 2023). "Reports studying the efficacy of several RTK inhibitors found the following inhibitors—imatinib, sunitinib, vandetanib, gefitinib, PI3K/mTOR inhibitors, BEZ-235, rapamycin, and p38 MAP kinase inhibitors (SB 202190 and SB 203580)—either inactive or less effective on chordoma cells." (PMID 37111759, 2023). "Subsequently, non-randomised phase II chordoma trials explored a combined treatment with imatinib and a mTOR inhibitor, but yielded moderate successes." (PMID 34550531, 2021). "Phosphorylation of mTOR, a key downstream mediator of RTK/Ras signaling in the mTORC1 and mTORC2 complexes that control ribosome biogenesis and protein synthesis, has been repeatedly found in chordoma." (PMID 31221659, 2019). "The same MTT regimen was also used against IM- and sunitinib-refractory chordoma but was not effective due to short of the mTOR expression." (PMID 30775316, 2019).
chordoma (continued). "The phenomenon that p70S6K was activated in p-mTOR negative chordomas was found in multiple studies." (PMID 22613809, 2011). "Importantly, efficient inhibition of the human chordoma cell line UCH-1 by PI-103, a dual PI3K and mTOR inhibitor, was recently reported." (PMID 22613809, 2011). "Furthermore, analysis of 22 chordomas by Tamborini and co-workers showed consistent ERK1/2 activation in all the cases, and activation of AKT in 20 (91%), mTOR in 18 (82%), and S6 in 16 (73%) of the tumors." (PMID 22613809, 2011). "The consistent activation of AKT, the frequent loss of the tumor suppressor PTEN allele, the recurrent activation of upstream RTK and of downstream effectors like p70S6K and mTOR, all indicate the PI3K/AKT pathway as an important mediator of transformation in chordomas." (PMID 22613809, 2011). "Approximately 50% of the p-mTOR-negative chordomas (16 of 33: 12 of which were immunoreactive for total mTOR) showed activation of neither p70S6K nor RPS6." (PMID 19401700, 2009). "The remaining 17 p-mTOR-negative chordomas were positive for p-p70S6K, 9 of 15 (60%) of which were immunoreactive for total mTOR, but only one of these cases was positive for RPS6." (PMID 19401700, 2009). "On the basis of this calculation, 35% of our chordomas would be unlikely to be responsive to mTOR antagonists." (PMID 19401700, 2009). "The complete absence of mTOR expression in nine chordomas raises the question as to how cells survive in the absence of ribosomal biogenesis." (PMID 19401700, 2009). "Commonly reported molecular targets in chordoma include platelet derived growth factor (PDGFR), vascular endothelial growth factor receptor (VEGFR), and epidermal growth factor receptor (EGFR), insulin-like growth factors (IGF), and mammalian target of rapamycin (mTOR)." (PMID 38881706, 2024). "Furthermore, an alternative avenue for the regulation of proliferation in chordoma cells involves the direct targeting of the mTOR pathway, a notable feature of which is the absence of PTEN." (PMID 38022609, 2023). "In addition, targeting PI3K-Akt-mTOR pathway worked well in TKI-resistant chordoma, and the combination of sirolimus plus imatinib significantly reduced the tumor size in imatinib-resistant chordoma patients." (PMID 36185236, 2022). "A body of such molecular, preclinical, and clinical evidence of interest to chordoma oncogenesis has begun to emerge for several kinases: Epidermal Growth Factor Receptor (EGFR), Cyclin-dependent kinase 4 (CDK4), Cyclin-dependent kinase 6 (CDK6) and the mammalian target of rapamycin (mTOR)." (PMID 32737414, 2020). "The combination of the antagonists of upstream RTKs and downstream mTOR/PI3K/MAPK/Stat not only synergistically reduced chordoma growth by avoiding the negative feedback loop and PI3K-dependent feedback loop, but also significantly decreased the cytotoxicity of either agent." (PMID 30775316, 2019). "Moreover, IHC staining and Western blot confirmed that although the mTOR expression in chordoma cells was relatively high, there was no statically significant difference in the expression levels of mTOR, PI3K, and AKt in different subtypes of clivus chordomas." (PMID 25793716, 2015). "We also tested the potential role of PI3K signaling in our zebrafish chordoma model using the PI3K inhibitor LY294002 and the PTEN inhibitor bpV(HOpic), but did not observe any inhibitory or activating effects on tumor growth, possibly due to PI3K-independent activation of mTOR by the RAS oncogene." (PMID 24311731, 2014). "Thirty-five of 48 chordomas were negative for p-mTOR; 30 of these could be analysed and 21 (70%) were immunoreactive for total mTOR." (PMID 19401700, 2009). "Interestingly, chordomas have been reported in patients with tuberous sclerosis complex (TSC), a multisystem syndrome due to TSC1 or TSC2 alterations resulting in constitutive mTOR hyperactivation, suggesting an etiological role of TSC gene alterations in chordomagenesis." (PMID 36983607, 2023).
chordoma (continued). "A variety of molecular targets may be relevant therapeutically in chordoma, including platelet-derived growth factor receptor (PDGFR), epidermal growth factor receptor (EGFR), vascular endothelial growth factor receptor (VEGFR), mammalian target of rapamycin (mTOR), and the INI1 gene." (PMID 32850452, 2020). "Most tumors were positive by immunohistochemistry for PDGFR-α (92%), PDGFR-β (85%), c-Kit (77%), c-Met (96%), pAKT (82%), mTOR (56%), HER2 (24%), and EGFR (26%), yet imatinib, an FDA-approved drug that inhibits PDGFR-α, PDGFR-β, and c-Kit, has shown little to no efficacy in chordoma in vivo models." (PMID 32737414, 2020).
kidney tumors (42 papers, 2008 to 2025). "The same mTOR gene mutation was identified in the liver metastasis and the primary renal tumor, as well as in the skull metastasis and the two renal tumors." (PMID 37938323, 2023). "We present a distinct renal tumor characterized by high-grade eosinophilic cells, cathepsin-K immunohistochemical expression, and harboring mTOR gene mutations demonstrating a malignant potential and showing responsiveness to mTOR inhibitors." (PMID 37938323, 2023). "In the past decade, several novel renal neoplasms characterized by mutations in the tuberous sclerosis complex (TSC) or mechanistic target of rapamycin (mTOR) pathway genes in both the sporadic and germline settings have been described." (PMID 37627070, 2023). "Another challenge is that some TSC/MTOR mutation-associated renal tumors fail to cleanly fit a given morphological/IHC-defined category." (PMID 37627070, 2023). "While remarkable progress has been made during the past decade in delineating TSC/MTOR mutation-related kidney tumors in both the hereditary and sporadic settings, several questions remain." (PMID 37627070, 2023). "Case 2 showed pathogenic mTOR alterations in both primary renal tumors and the skull metastasis involving the exon 53 (p.Leu2427Arg—COSM2119114)." (PMID 37938323, 2023). "A spectrum of renal tumors associated with frequent TSC/mTOR (tuberous sclerosis complex/mechanistic target of rapamycin) pathway gene alterations (in both the germline and sporadic settings) have recently been described." (PMID 37627070, 2023). "Unlike other hereditary syndromes, such as von Hippel–Lindau disease (VHL) and hereditary leiomyomatosis and renal cell carcinoma (HLRCC), histologic manifestations of renal tumors associated with TSC/mTOR pathway alterations are heterogenous." (PMID 37627070, 2023). "Based on current evidence, we do not think that entities such as ESC RCC, LOT, and EVT should be grouped as “TSC/MTOR mutation-associated renal tumors”." (PMID 37627070, 2023). "Despite the common genetic background, it appears that the tumors with TSC/mTOR mutations represent a diverse group of distinct renal neoplasms." (PMID 35203531, 2022). "These sporadic renal tumors associated with TSC/mTOR pathway alteration appear to form a heterogeneous group of tumors with distinct morphological features and immunohistochemical profiles but different biological behaviors." (PMID 35203531, 2022). "PGAM1 was elevated in mouse kidney tumor caused by up-regulated mTOR due to Tsc2 exon 3 deletion (Tsc2del3/+) compared with its adjacent kidney tissue." (PMID 29362480, 2018). "Activation of the TSC 2 and folliculin genes in mice has been associated with both renal tumour development and mammalian target of rapamycin (mTOR) dysregulation." (PMID 28326270, 2015). "Consistent with this possibility, we found that clinical renal tumors had increased expression of genes associated with mTOR activity that were both sensitive and insensitive to mTORC1 inhibition." (PMID 23349989, 2013). "It is known that the Tsc2-/- tumors in this mouse model have constitutively activated mTOR kinase, and a similar defect in mTOR signaling is observed in brain and kidney tumors associated with TSC." (PMID 18226258, 2008). "Recently, several renal tumors harboring mTOR gene mutations have been described." (PMID 37938323, 2023). "The rapidly expanding spectrum of TSC/MTOR mutation-associated renal tumors may pose diagnostic challenges for general pathologists given the rarity of some of the entities, the overlap in morphologic features, and the limited availability of some IHC stains." (PMID 37627070, 2023). "PIK3CA and MTOR genes show gain-of-function mutations in about 2.5 and 6%, respectively, of renal tumors (COSMIC database), and the inhibition of the major effectors of the pathway (PI3K catalytic subunits, AKT, mTOR) is under intense exploration in clinical trials." (PMID 37147361, 2023).